FBXL17 (F-box and leucine rich repeat protein 17)
Description:
Substrate-recognition component of the SCF(FBXL17) E3 ubiquitin ligase complex, a key component of a quality control pathway required to ensure functional dimerization of BTB domain-containing proteins (dimerization quality control, DQC). FBXL17 specifically recognizes and binds a conserved degron of non-consecutive residues present at the interface of BTB dimers of aberrant composition: aberrant BTB dimer are then ubiquitinated by the SCF(FBXL17) complex and degraded by the proteasome. The ability of the SCF(FBXL17) complex to eliminate compromised BTB dimers is required for the differentiation and survival of neural crest and neuronal cells (By similarity). The SCF(FBXL17) complex mediates ubiquitination and degradation of BACH1. The SCF(FBXL17) complex is also involved in the regulation of the hedgehog/smoothened (Hh) signaling pathway by mediating the ubiquitination and degradation of SUFU, allowing the release of GLI1 from SUFU for proper Hh signal transduction. The SCF(FBXL17) complex mediates ubiquitination and degradation of PRMT1 (By similarity).
Synonyms: FBL17; FBX13; FBXO13; DKFZP434C1715
Tractability: PROTAC: ubiquitination databases record sites on it.
Gene: Protein-coding gene on chromosome 5 (107,859,035 to 108,382,098, reverse strand). Ensembl gene ENSG00000145743.
Subcellular location: Cytoplasm; Nucleus
Subcellular location (Human Protein Atlas): Nucleoplasm
Pathways (Reactome):
Cellular responses to stimuli: Regulation of BACH1 activity
Gene Ontology:
Molecular function: protein binding
Biological process: proteasome-mediated ubiquitin-dependent protein catabolic process; protein polyubiquitination; protein quality control for misfolded or incompletely synthesized proteins; protein ubiquitination; regulation of smoothened signaling pathway; SCF-dependent proteasomal ubiquitin-dependent protein catabolic process; nervous system development; neural crest cell differentiation
Cellular component: cytoplasm; nucleoplasm; nucleus; SCF ubiquitin ligase complex
Genetic constraint (gnomAD): Loss-of-function variants: 16 observed, 35.85 expected, observed/expected ratio (o/e) 0.45, 90% interval 0.3 to 0.68. The synonymous counts are far from expectation, so gnomAD's model fits this gene poorly and the ratio says little. Missense variants: 794 observed, 616.34 expected, observed/expected ratio (o/e) 1.29, 90% interval 1.22 to 1.37. Synonymous variants: 416 observed, 267.65 expected, observed/expected ratio (o/e) 1.55, 90% interval 1.43 to 1.69.
Homologues: Orthologues: macaque FBXL17 (98% identical), pig FBXL17 (96% identical), chimpanzee FBXL17 (94% identical), mouse Fbxl17 (93% identical), rat Fbxl17 (93% identical), dog FBXL17 (79% identical), tropical clawed frog fbxl17 (36% identical), zebrafish fbxl17 (26% identical), Drosophila melanogaster CG9003 (12% identical), Drosophila melanogaster Skp2 (11% identical), Caenorhabditis elegans gadr-5 (11% identical), Caenorhabditis elegans zeel-1 (11% identical), and 22 more. Paralogues in human: FBXL7 (13% identical), FBXL13 (13% identical), FBXL16 (12% identical), FBXL19 (11% identical), FBXL2 (11% identical), FBXL4 (10% identical), FBXL20 (10% identical), FBXL5 (10% identical), FBXL6 (10% identical), FBXL18 (9% identical), FBXL14 (9% identical), SKP2 (8% identical), and 3 more.
Diseases named in the same sentence as FBXL17 in open-access papers:
FBXL17 is named in the same sentence as 28 diseases in open-access papers, as found by Europe PMC text mining. Sharing a sentence is not in itself a finding about the gene and the disease. The quoted sentences say what the papers report.
breast carcinoma (5 papers, 2015 to 2022). "In summary, FBXL17 is broken in approximately 7% of breast cancers, and additionally rearranged or mutated in other epithelial cancers." (PMID 31560077, 2020). "The 5q loss also includes FBXL17, a gene reported to be a biomarker for breast cancer resistance, and MEF2C, which was previously identified in association with breast cancer invasion." (PMID 25391423, 2015). "The UAP1 activity can be inhibited by Fbxl17 through blocking the phosphorylation status of UAP1 in breast cancer." (PMID 36158580, 2022). "Knockdown of Fbxl17 expression elevated O-GlcNAcylation in breast cancer cells, arguing for a functional role for Fbxl17 in this metabolic pathway." (PMID 31560077, 2020). "We found FBXL17 was rearranged in around 7% of breast cancers according to array-CGH, and also in cancer cell lines." (PMID 31560077, 2020). "We found FBXL17 is rearranged in breast cancers, and these rearrangements often disrupt the LRRs of Fbxl17." (PMID 31560077, 2020). "Our data support a model whereby Fbxl17 has tumour suppressor activity in breast cancers." (PMID 31560077, 2020). "In addition to breaks in tumours, array-CGH data showed breaks in FBXL17 in four cancer cell lines, the breast carcinoma cell lines, BT-474, HCC38, and HCC1395, and the oesophageal/gastric cardia adenocarcinoma line OE-19." (PMID 31560077, 2020). "Thus in the context of breast cancer, the rearrangements that target the LRRs of FBXL17 would likely diminish ubiquitination of the network of SCFFbxl17 substrates." (PMID 31560077, 2020). "From two pairs of matched breast cancer samples, we found that some of the detected CNVs contained some genes that were related to breast cancer, such as PDZK1, XRCC4, Fbxl17, ITGBL1, RORA, BAGE, AMOTL1, RAP80, PIWIL4, CSE1L, and USP18." (PMID 34262604, 2021). "Because the cell line examples may not be typical, we looked for examples of FBXL17 rearrangements in breast cancers, in paired-end whole-genome DNA sequencing data from 250 primary breast tumours of the Cambridge Personalised Breast Cancer Programme." (PMID 31560077, 2020).
Gorlin syndrome (2 papers, 2016 to 2021). "Furthermore, this study identifies S352F mutation of Sufu, occurring in MB of patients with Gorlin syndrome, destabilizes Sufu through enhanced binding to Fbxl17, highlighting the perturbation of the Fbxl17-Sufu axis in the pathogenesis of MB." (PMID 34948134, 2021). "Finally, we show that in human disease, a somatic mutation in Sufu, occurring in medulloblastoma of patients with Gorlin syndrome, increases Sufu turnover through Fbxl17 polyubiquitylation, leading to a sustained Hh signaling and cell proliferation." (PMID 27234298, 2016). "Furthermore, we identify a mutation in Sufu, occurring in medulloblastoma of patients with Gorlin syndrome, which increases Sufu turnover through Fbxl17‐mediated polyubiquitylation and leads to a sustained Hh signaling activation." (PMID 27234298, 2016).
medulloblastoma (2 papers, 2016 to 2022). A malignant, invasive embryonal neoplasm arising from the cerebellum. "To establish a role for Fbxl17 in the etiology of medulloblastoma through Sufu mutation, we investigated in more detail the Sufu S352F substitution, which favors binding to Fbxl17." (PMID 27234298, 2016). "Depletion of Fbxl17 leads to defective Hh signaling associated with an impaired cancer cell proliferation and medulloblastoma tumor growth." (PMID 27234298, 2016). "A more direct role of Hh pathway has been established in the pathogenesis of medulloblastoma characterized by the presence of mutations in central components of Hh signaling; therefore, we tested whether the Fbxl17–Sufu axis operates in medulloblastoma cancer cells." (PMID 27234298, 2016). "Our study highlights the alteration in Fbxl17–Sufu axis as an etiological mechanism of medulloblastoma." (PMID 27234298, 2016). "Extending our basic biological finding to the significance of the Fbxl17–Sufu axis in vivo, we have identified Fbxl17 as a crucial regulator of cell proliferation in medulloblastoma." (PMID 27234298, 2016). "To investigate the relevance of Fbxl17–Sufu axis in cancer, we assessed the effect of RNAi of Fbxl17 in vivo by using an orthotopic rat model of medulloblastoma." (PMID 27234298, 2016). "In summary, our findings reveal Fbxl17 as a novel regulator of Hh pathway and highlight the perturbation of the Fbxl17–Sufu axis in the pathogenesis of medulloblastoma." (PMID 27234298, 2016). "Inhibition of Fbxl17 blocks Sufu degradation, Hh pathway activation and prevents medulloblastoma tumor growth." (PMID 27234298, 2016). "In the absence of Sufu mRNA alterations, these results suggest that in medulloblastoma the control of Sufu protein levels by Fbxl17 plays a prominent role in sustaining Hh activation." (PMID 27234298, 2016). "Strikingly, Fbxl17 mRNA was found to be significantly increased in the SHH‐subtype medulloblastoma and the levels of Fbxl17 and Gli1 positively correlated (Spearman's rho = 0.5640; P < 0.00001)." (PMID 27234298, 2016). "Given the relevant role of Fbxl17 in Hh signaling and medulloblastoma growth, we analyzed the mRNA expression of Fbxl17 and Sufu reported in the largest published medulloblastoma expression profiling study (N = 285 primary samples)." (PMID 27234298, 2016). "In medulloblastoma, the combination of Smo inhibitors and Fbxl17 inhibitors could be a viable alternative strategy to obtain sustained responses." (PMID 27234298, 2016). "Importantly, mutations in other components of Hh signaling pathway, such as Ptch (present in > 50% of SHH medulloblastoma), will also affect Sufu protein levels, given the effect of pathway activation on Sufu protein mediated by Fbxl17." (PMID 27234298, 2016). "Thus, our study highlights Fbxl17 as a novel target for the treatment of SHH medulloblastoma." (PMID 27234298, 2016). "In SHH medulloblastoma, the substrate adaptor F-box/LRR-repeat protein 17 (Fbxl17) assembles into a functional SCFFbxl17 to promote the ubiquitylation-dependent degradation of the tumour suppressor Suppressor of fused homologue (SUFU), acting as a bona-fide oncoprotein." (PMID 35379950, 2022).
breast tumours (1 paper, 2020). "Kaplan–Meier analysis for these genes revealed that breast tumours with either low Fbxl17 expression, or high Uap1 expression were associated with poorer survival in patients." (PMID 31560077, 2020).
colorectal cancer (1 paper, 2016). A primary or metastatic malignant neoplasm that affects the colon or rectum. "Other mutations of Sufu residing in critical residues for Fbxl17 binding have been described in colorectal cancer and malignant melanoma; thus, alteration in Fbxl17–Sufu axis could be present in other cancer types." (PMID 27234298, 2016).
coronary heart disease (1 paper, 2022). "Single-nucleotide polymorphism in FBXL17 gene in Lithuanian families has been correlated with coronary heart disease earlier." (PMID 35625658, 2022).
lung adenocarcinoma (1 paper, 2021). A carcinoma that arises from the lung and is characterized by the presence of malignant glandular epithelial cells. "Of note, according to a recent case report, a novel ROS1-FBXL17 (F-box and leucine-rich repeat protein 17) fusion, co-existing with CD74-ROS1 fusion was detected in a patient with lung adenocarcinoma, possibly improving sensitivity to crizotinib." (PMID 33572278, 2021).
oesophageal adenocarcinoma (1 paper, 2020). "Rearrangements of FBXL17 have also been detected in other epithelial cancers including prostate and oesophageal adenocarcinoma." (PMID 31560077, 2020).
osteosarcoma (1 paper, 2021). A usually aggressive malignant bone-forming mesenchymal neoplasm, predominantly affecting adolescents and young adults. "EFNA5 was implicated in repairing the DNA damage induced by ionizing radiation, and FBXL17 is involved in U2OS osteosarcoma cellular sensitivity to ionizing radiation." (PMID 34838041, 2021).
prostate carcinoma (1 paper, 2016). A carcinoma that arises from epithelial cells of the prostate gland. "Since proliferation of PC3 cells is in part dependent on Hh signaling pathway, we evaluated whether Fbxl17 depletion impairs the prostate cancer cell proliferation." (PMID 27234298, 2016). "The interaction between endogenous Fbxl17 and Sufu was validated in PC3 (human prostate cancer cell line) and DAOY (medulloblastoma cancer cell line), indicating that Fbxl17 and Sufu interact specifically, physiologically, and in different cell lines." (PMID 27234298, 2016).
severe combined immunodeficiency (1 paper, 2021). Severe combined immunodeficiency (SCID) comprises a group of rare monogenic primary immunodeficiency disorders characterized by a lack of functional peripheral T lymphocytes resulting in early-onset severe respiratory infections and failure to thrive. "Using GeneCards and MalaCards, showed EFNA5, FBXL17, and FER have been associated with severe combined immunodeficiency characterized by sensitivity to ionizing radiation disease, DNA damage response after ionizing radiation and activation of the ataxia-telangiectasia mutated protein, respectively." (PMID 34838041, 2021).
uveal melanoma (1 paper, 2025). A melanoma derived from melanocytes of the uveal tract. "Furthermore, within the scope of the same study, a set of genes including DERL1, FBXL17, MBOAT2,PLAG, SLC7A, and YTHDF3 were identified as target genes susceptible to modulation by miR-181b-5p in tumor tissue of uveal melanoma patients." (PMID 38914847, 2025).
cancer (9 papers, 2016 to 2026). A tumor composed of atypical neoplastic, often pleomorphic cells that invade other tissues. "Reducing Fbxl17 levels results in increased O-GlcNAcylation levels in cells, a phenomenon already reported in numerous cancer types and associated with poorer prognosis." (PMID 33234069, 2020). "Fbxl17 mRNA was found to be significantly increased in the SHH-subtype MB and the levels of Fbxl17 and Gli1 positively correlated; depletion of Fbxl17 reduced Hh signaling through stabling Sufu, attenuated cancer cell proliferation and MB tumor growth." (PMID 34948134, 2021). "The most downregulated FBXL protein is Fbxl17 whose expression is decreased in almost all cancer types examined." (PMID 33234069, 2020). "In conclusion, by surveying structural rearrangements in cancer databases, we discovered rearrangements commonly occur in FBXL17 which affect its ability to bind substrates and also assemble as part of a functional SCF ubiquitin ligase complex." (PMID 31560077, 2020). "Overexpression of Fbxl17 in SHH subgroups provides a therapeutic window to selectively target cancer cells." (PMID 27234298, 2016). "The loss-of-function mutations in FBXL17 caused by structural rearrangements could have additional effects on the cell, since the targets of Fbxl17 are involved in major, cancer-relevant cellular processes." (PMID 31560077, 2020). "These more global destabilizing effects may explain the greater incidence of downregulated Fbxl17 expression in cancers more generally." (PMID 33234069, 2020). "There are not yet enough data on rearrangement of FBXL17 in cancers to conclusively identify FBXL17 inactivation as a driver mutation in cancer." (PMID 31560077, 2020). "Thus, genomic rearrangements in FBXL17 are likely to disrupt SCFFbxl17-regulated networks in cancer cells." (PMID 31560077, 2020). "Nonetheless, we were able to show a striking effect of reducing Fbxl17 expression on at least one important cancer-relevant pathway, in a relevant cell type, suggesting that inactivation of Fbxl17 would have a major effect on the cancer cell." (PMID 31560077, 2020). "In these cancers, increasing Sufu levels through Fbxl17 inhibition could block Hh signaling and cell proliferation." (PMID 27234298, 2016). "Our studies suggest that compounds that could modify the BTB or DNA-binding domains of BACH1 have the potential to promote the ubiquitination and degradation of BACH1 by FBXL17 or FBXO22, thereby, ameliorating BACH1-mediated cancer metastasis." (PMID 38895309, 2024). "Although the number of cases is small, these data suggest Fbxl17 is not rearranged in a particular cancer subtype." (PMID 31560077, 2020).
tumor (6 papers, 2016 to 2025). "Collectively these data show that although the loss of Fbxl17 in tumours can affect individual signalling pathways, it would also cause more widespread intracellular changes to protein homeostasis, heme metabolism and post-translational modifications." (PMID 33234069, 2020). "Independently, analysis of sequence-level mutation data also suggested that FBXL17 behaves like a tumour suppressor gene." (PMID 31560077, 2020). "Rearrangements (‘Structural variants’) in FBXL17 were identified in five of the tumours." (PMID 31560077, 2020). "In this light, it is worth considering the substrates of Fbxl17 in relation to how the loss of Fbxl17 may promote tumour development." (PMID 33234069, 2020). "In vivo T2‐weighted magnetic resonance imaging (MRI) showed a marked reduction in tumor progression over time with RNAi against Fbxl17." (PMID 27234298, 2016). "However, in this instance, Fbxl17 is upregulated in a subtype of medulloblastoma tumours and thus functions as an oncogene." (PMID 33234069, 2020).
cardiovascular diseases (1 paper, 2022). "SIRPA and FBXL17 are both biologically plausible candidates for cardiovascular diseases and there are several possible explanations for why these associations have not been identified in European and Asian populations." (PMID 35165267, 2022).
endocrinopathies (1 paper, 2014). "One of these variants, the N309K mutation in the PCSK1 gene, appeared to be the probable cause of the CDD and endocrinopathies, given that other mutations in PCSK1 are known to cause similar symptoms, whereas the other three variants (HADHA, FBXL17 and GTF3C2) are not known to be involved in CDD." (PMID 25272002, 2014).
FBXL17 also shares sentences with these, for which no sentence is quoted: arthropathy (1 paper); atherosclerosis (1); cardiac hypertrophy (1); diabetes (1); epilepsy (1); gastric cardia adenocarcinoma (1); heart failure (1); hereditary spastic paraplegia (1); malignant melanoma (1); nicotine dependence (1); Obesity (1); xerostomia (1).